RAD51D (RAD51 paralog D)
Diseases named in the same sentence as RAD51D in open-access papers (continued):
Sharing a sentence is not in itself a finding about the gene and the disease.
gastric cancer (4 papers, 2022 to 2025). A primary or metastatic malignant neoplasm involving the stomach. "To this end, we intersected the gastric cancer diagnostic biomarkers screened by each machine learning method and obtained RAD51D and XRCC2." (PMID 39206620, 2024). "Our study identified RAD51D as a diagnostic biomarker for gastric cancer and validated it in gastric cancer tissues and cell lines." (PMID 39206620, 2024). "Deletion of any of these genes increases the AIC, and RAD51D contributes the most to the AIC of the diagnostic prediction model for gastric cancer." (PMID 39206620, 2024). "In the previous results, qRT‐PCR assays measured the expression of RAD51D with XRCC2 in 39 gastric cancer patients." (PMID 39206620, 2024). "Using machine learning, we screened RAD51D and XRCC2 in the homologous recombination pathway as diagnostic biomarkers for gastric cancer." (PMID 39206620, 2024). "Indeed, this patient presented the typical clinical picture of hereditary gastric cancer, suggesting RAD51D as a possible candidate gene for this condition, as previously proposed for RAD51C." (PMID 37239438, 2023). "The gastric cancer diagnostic biomarkers RAD51D and XRCC2 that we screened can, to a certain extent, reflect the expression status of genes through radiomic characteristics, which is of certain significance in guiding the selection of chemotherapy regimens for gastric cancer patients." (PMID 39206620, 2024). "The mRNA levels of RAD51D and XRCC2 in gastric cancer tissues were significantly greater than those in adjacent tissues (p < 0.001)." (PMID 39206620, 2024). "The results revealed that there was a significant positive correlation between the expression of RAD51D and XRCC2 and the pathological T stage of gastric cancer." (PMID 39206620, 2024). "The results showed that RAD51D was not a risk factor for gastric cancer, but other BRCA1, BRCA2, and ATM genes from the homologous recombination pathway are risk factors for gastric cancer." (PMID 39206620, 2024). "We screened RAD51D and XRCC2 in the homologous recombination pathway as biomarkers for gastric cancer diagnosis by machine learning, and the expression of RAD51D and XRCC2 was significantly positively correlated with pathological T stage, N stage, and TNM stage." (PMID 39206620, 2024). "In addition, we used the TCGA database to verify that after pairing RAD51D and XRCC2, the mRNA level in gastric cancer tissue was still significantly greater than that in adjacent tissue (p < 0.001)." (PMID 39206620, 2024). "Strikingly, regardless of which kind of gastric cancer prediction model is built by machine learning, RAD51D has the most prominent contribution to the accuracy of the prediction model." (PMID 39206620, 2024). "Moreover, our study showed that the expression of RAD51D and XRCC2 was significantly and positively correlated with the clinicopathological features of gastric cancer patients." (PMID 39206620, 2024). "Therefore, we could predict the expression status of RAD51D and XRCC2 during homologous recombination to reflect the sensitivity of gastric cancer patients to platinum chemotherapy drugs." (PMID 39206620, 2024). "RAD51D expression was not significantly correlated with vascular thrombus or nerve invasion, while XRCC2 expression was greater in gastric cancer patients with vascular thrombus or nerve invasion (p < 0.05)." (PMID 39206620, 2024).
colon cancer (2 papers, 2016 to 2021). "RAD51D, involved in DNA repair, has been found to be rarely mutated in ovarian, breast, and colon cancer." (PMID 34712603, 2021).
hereditary cancer syndromes (2 papers, 2020 to 2023). "We identified two point mutations in KDM6A, which had not previously been identified in medulloblastomas, and validated germline mutations in BRCA2, RAD51D and ATM, which are all involved in DNA repair of double-stranded breaks as well as hereditary cancer syndromes." (PMID 37576901, 2023).
melanoma (2 papers, 2020 to 2025). A malignant, usually aggressive tumor composed of atypical, neoplastic melanocytes. "In RAD51D-positive families, two male patients with lung and melanoma cancers in the BOC-3784 family were carriers of PVs." (PMID 40282418, 2025). "Altogether, 7/11 double mutation carriers (excluded from the analysis of clinicopathological data) carried at least one mutation in high-risk melanoma (POT1/CHEK2) or syndromic (ATM/WRN, BRCA1, BRCA2 (2x), CHEK2/RAD51D, NBN) genes." (PMID 33050356, 2020).
osteosarcoma (2 papers, 2019 to 2024). A usually aggressive malignant bone-forming mesenchymal neoplasm, predominantly affecting adolescents and young adults. "Given that CHO cells deficient for RAD51C, RAD51D, XRCC2 or XRCC3, and human HCT116 cells deficient for XRCC3 are viable, we attempted to disrupt each classical RAD51 paralog individually in transformed human osteosarcoma U2OS and human embryonic kidney HEK293 cells." (PMID 31584931, 2019).
ovarian tumors (2 papers, 2022 to 2025). "RAD51D mutation carriers were more likely to suffer from premenopausal ovarian tumors." (PMID 36544182, 2022). "Although the role of RAD51D is unclear in this context, germline RAD51D carriers have been reported to develop ovarian tumors at an early age." (PMID 40981433, 2025).
sarcoma (2 papers, 2021 to 2022). A usually aggressive malignant neoplasm of the soft tissue or bone. "In conclusion, we present a case of recurrent leiomyosarcoma in the peritoneum that showed evidence of a germline background for the RAD51D splicing variant in intron 9 implies the clinical risk elevation for malignant tumors, including sarcomas." (PMID 34838098, 2021). "We present the findings of a case of leiomyosarcoma in the peritoneum of a female patient with a novel germline splicing variant of RAD51D as potential evidence for the pathogenicity of the variant and its involvement in the risk of sarcoma etiology and/or development." (PMID 34838098, 2021). "Although gynecological non-epithelial tumors such as uterine sarcomas are associated with genomic instability, including BRCA impairment, there is no clear evidence of the relationship between RAD51D variants and the risk of sarcoma development." (PMID 34838098, 2021). "Overall, in this case, the non-compensated steady level of RAD51 plus abnormal RAD51D protein production due to its splicing variant might have transformed the tissue phenotypes into a highly aggressive type of sarcoma." (PMID 34838098, 2021). "BRCA1, RAD51D, and additionally XRCC2 were downregulated in the M6 high-grade sarcoma, whereas XRCC3 was highly overexpressed." (PMID 35978432, 2022).
bowel cancer (1 paper, 2021). "In this case-control study, mutations in 8 genes (APC, ATM, MLH1, FANCD2, MSH3, MSH6, PMS1, and RAD51D) were found to be associated with bowel cancer and were present in 3.5% of patients with bowel cancer." (PMID 35154239, 2021).
cervical cancer (1 paper, 2021). A primary or metastatic malignant neoplasm involving the cervix. "Genes with known or likely deleterious variants among cervical cancer patients with DDR gene alterations were ATM (n = 3, 2.33%), BRCA2 (n = 3, 2.33%), ATR (n = 2, 1.55%), CHEK2 (n = 2, 1.55%), followed by BRCA1 (n = 1, 0.78%), FANCA (n = 1, 0.78%), MSH6 (n = 1, 0.78%), and RAD51D (n = 1, 0.78%)." (PMID 35071000, 2021).
clear cell renal cell carcinoma (1 paper, 2020). "Ten pathogenic or likely pathogenic (P/LP) variants were identified in 11 sporadic clear cell renal cell carcinoma patients (10.38%), including rarely reported ATM (n=1), MUTYH (n=1), NBN (n=1), RAD51D (n=1), and BRCA2 (n=1)." (PMID 33062672, 2020).
hepatocellular carcinoma (1 paper, 2019). A malignant tumor that arises from hepatocytes. "This study is aimed to investigate the associations between RAD51D polymorphisms and the hereditary susceptibility of hepatocellular carcinoma (HCC)." (PMID 30883040, 2019).
leiomyosarcoma (1 paper, 2021). An uncommon, aggressive malignant smooth muscle neoplasm, usually occurring in post-menopausal women. "The peritoneal tumor was histologically diagnosed as a leiomyosarcoma and was genetically identified to show a splice variant of RAD51D c.904-2A > T [NM_002878] through tumor profiling performed as a part of cancer precision medicine." (PMID 34838098, 2021). "We report the findings of this rare case with possible involvement of the germline variant of RAD51D c.904-2A > T as a potential predisposing factor for malignant tumors, including leiomyosarcoma." (PMID 34838098, 2021).
liver cancer (1 paper, 2025). An epithelial or non-epithelial malignant neoplasm that arises from the liver. "Although the mutation status of RAD51D has not been corroborated among kindred, other types of cancer reported in RAD51D-positive families include CRC, gastric, pancreatic, and liver cancers." (PMID 40282418, 2025).
lymph node metastasis (1 paper, 2024). "The expression levels of RAD51D and XRCC2 were significantly correlated with pathological T stage, N stage, number of lymph node metastases, lymph node metastasis rate, TNM stage, and Lauren's classification (p < 0.05)." (PMID 39206620, 2024).
non-small cell lung carcinoma (1 paper, 2017). A group of at least three distinct histological types of lung cancer, including non-small cell squamous cell carcinoma, adenocarcinoma, and large cell carcinoma. "Herein, we took advantage of TCGA data, screening candidate DNA-repair genes (RAD51B, RAD51C, RAD51D, XRCC2, and XRCC3) with covariance and correlation matrices in mRNA level from complete 1124 complete cases of non-small cell lung cancer clinical data." (PMID 29207658, 2017).
ovarian carcinosarcoma (1 paper, 2022). A highly aggressive malignant neoplasm arising from the ovary. "A heavily treated ovarian carcinosarcoma (OCS) was found to respond to a PARP inhibitor with a RAD51D mutation." (PMID 36290878, 2022).
cancer (114 papers, 2012 to 2026). A tumor composed of atypical neoplastic, often pleomorphic cells that invade other tissues. "Knowledge about RAD51C and RAD51D mutations is important for identifying individuals at increased risk of cancer for early detection and screening." (PMID 39202057, 2024). "At present, research on RAD51D has mainly assessed the relationship between germline pathogenic variants and cancer risk, and there is a lack of research on the specific molecular mechanisms by which RAD51D causes cancer." (PMID 39206620, 2024). "Only 2 cases out of the 13 had heterozygous germline variants in cancer predisposition genes (RAD51D, BRIP1)." (PMID 37869077, 2023). "Cells deficient in RAD51D are sensitive to treatment with a PARPi, suggesting a possible therapeutic approach for cancers arising in RAD51D mutation carriers." (PMID 36544182, 2022). "Previous studies have also demonstrated that biallelic loss in BRIP1 or RAD51D is associated with a higher gwLOH score in BRCA-associated cancers." (PMID 35643464, 2022). "Whilst RAD51C and RAD51D are now established cancer predisposition genes, loss-of-function germline variants in RAD51B have only been reported in individual cases of breast and ovarian cancer." (PMID 34635660, 2021). "We also present a case in which the RAD51D variant was identified as a presumed germline pathogenic variant (PGPV) in cancer precision medicine and was successfully referred for genetic counseling including the patient’s family members in a timely manner." (PMID 34838098, 2021). "The results presented here imply that cancer family history should be considered when counseling carriers with RAD51C or RAD51D pathogenic variants because it can lead to large differences in the cumulative TOC and BC and thus influence clinical management." (PMID 32107557, 2020). "This revealed an increase in RAD51B, RAD51C and RAD51D paralogue mutations in human cancers." (PMID 42133623, 2026). "An analysis of RAD51D mutations revealed five distinct PVs in twelve hereditary cancer families." (PMID 40282418, 2025). "Although the role of RAD51C and RAD51D have yet to be fully explored in the FC population, it is clear from previous work that investigating the FC population can assist in characterizing new cancer risk genes." (PMID 35565380, 2022). "Germline variants in the HR pathway, comprising at least 10 genes, such as BRCA1, BRCA2, ATM, BARD1, BRIP1, CHEK2, NBS1(NBN), PALB2, RAD51C, and RAD51D, lead to inherited susceptibility to specific types of cancers, including those of the breast, ovaries, prostate, and pancreas." (PMID 35008774, 2021). "The association between Rad51D and hypoxia has been demonstrated in cancer." (PMID 23819581, 2013). "A failure of this repair pathway that could be expected in cancer patients carrying germline pathogenic mutations in RAD51C and RAD51D sensitizes cancer cells to PARP inhibitors; therefore, patients carrying germline RAD51C and RAD51D mutations may benefit from this therapy." (PMID 26057125, 2015). "Materials and Methods: Families harbouring PVs in RAD50, RAD51C, RAD51D, and BRIP1 were identified by analysing a cancer-predisposing genes panel using Ion S5 system technology." (PMID 40282418, 2025). "Other mutations responsible for the development of this cancer are germline mutations in the BRIP1, RAD51C, or RAD51D genes." (PMID 40429755, 2025). "Among other cancer susceptibility genes, associations were seen for ATM (p = 0.0013), BRCA1 (p = 0.0015), BARD1 (p = 0.00021), CHEK2 (p = 0.039), RAD51D (p = 0.0065), MSH3 (p = 0.0025)." (PMID 39749474, 2025). "In contrast, data on cancer risk for PALB2, RAD51C, and RAD51D GPV carriers are limited and lifetime cancer risks largely depend on both family history and personal risk factors, such as age of menarche, use of oral contraceptives, and the number of children." (PMID 40428378, 2025).
cancer (continued). "The increased sensitivity of RAD51D-mutated cells to Olaparib, a poly(ADP-ribose) polymerase inhibitor (PARPi), confirmed the opportunity for targeted treatments of cancers associated with RAD51D." (PMID 39202057, 2024). "In a cohort of Italian MBC (523 patients) analysed with a panel of 50 cancer-associated genes, PALB2 and RAD51D gene variants were significantly associated with MBC risk." (PMID 37762649, 2023). "The proportion of germline SV mutations in BRCA1 and BRCA2 was markedly elevated in OC (BRCA1, 3.4%; BRCA2, 1.7%) and PC (BRCA2, 2.2%) compared to other cancers, as was the proportion of germline SV mutations in the HR genes RAD51C and RAD51D in OC." (PMID 37821580, 2023). "In contrast, the tumour with bi-allelic BRCA2 inactivation and RAD51D c.202G > A (tumour 46) was classified as BRCA2-like supporting the inactivation of BRCA2 as the driver of this cancer." (PMID 37316882, 2023). "Overall, 15 patients out of 521 (2.9%) showed PVs and LPVs in five cancer-predisposing genes other than BRCA1/2 (PALB2, CHEK2, ATM, RAD51C, and RAD51D)." (PMID 37628581, 2023). "PARPi activity was also demonstrated for BRCAwt cancers due to mutations in genes critical for DNA repair (e.g., ATM, BARD1, BRIP1, CHEK2, NBN, PALB2, RAD51C, and RAD51D)." (PMID 36910637, 2023). "For each patient, we also showed the risk in the well-known high-penetrance cancer risk alleles BRCA1 and BRCA2 with respect to other moderate-penetrance alleles including PALB2, CHEK2, ATM, BARD1, RAD51D, RAD51C and BRIP1." (PMID 35886069, 2022). "But the most remarkable pro-cancer RAD52 phenotype is seen in cancer cells deficient in any of the following DNA repair proteins: BRCA1, BRCA2, PALB2, XAB2 or RAD51 paralogs: RAD51B, RAD51C, RAD51D, XRCC2 and XRCC3." (PMID 34887904, 2021). "Genes that are essential in eHAP cells include cancer risk genes such as PALB2, BARD1, RAD51C, and RAD51D, which have thousands of variants recorded in ClinVar." (PMID 33691754, 2021). "In this analysis, we evaluated the clinical presentation of over 3000 women with PVs in BRIP1, RAD51C, or RAD51D identified by a multigene hereditary cancer panel." (PMID 33926482, 2021). "In contrast to this, monoallelic variants of the RAD51 gene and of five of its paralogs have recently been involved in cancer predisposition: RAD51B, RAD51C, and RAD51D in OC; RAD51, RAD51B, and XRCC2 in BC." (PMID 32046255, 2020). "The pathogenic variant population frequencies used in the segregation analysis model were estimated to be 0.00022 for RAD51C and 0.00026 for RAD51D based on 42 325 cancer-free individuals from the UK Biobank exome sequencing data." (PMID 32107557, 2020). "Here, we use a large collection of families with RAD51C and/or RAD51D pathogenic variants to estimate age-specific TOC and BC risks and assess how these vary by family history of cancer." (PMID 32107557, 2020). "These estimates will facilitate the genetic counseling of RAD51C and RAD51D pathogenic variant carriers and justify the incorporation of RAD51C and RAD51D into cancer risk prediction models." (PMID 32107557, 2020). "In contrast to RAD51C and RAD51D, XRCC2, XRCC3 and RAD51B variants are less frequently observed in tumors and the cancer risk for individuals harboring these variants remains controversial." (PMID 33015624, 2020).